SHANK3 (SH3 and multiple ankyrin repeat domains 3)
Diseases named in the same sentence as SHANK3 in open-access papers (continued):
Sharing a sentence is not in itself a finding about the gene and the disease.
Intellectual disability (continued). "SHANK3 is the critical gene in this syndrome, and studies indicate that loss of one copy of SHANK3 causes a monogenic form of ASD with a frequency of at least 0.5% of ASD cases and up to 2% of ASD with moderate to profound intellectual disability." (PMID 34593045, 2021). "Most individuals with SHANK3 intragenic variants have been described as having autism spectrum disorder (ASD) and/or intellectual disability." (PMID 33407854, 2021). "Intragenic SHANK3 deletion is a probable etiology for the observed intellectual disability, disharmonic organization of personality, significant sleep disturbance, seizures, and other symptoms." (PMID 34228749, 2021). "Mutation in the SHANK3 human gene leads to different neuropsychiatric diseases, including ASD, schizophrenia, intellectual disability, and Phelan–McDermid syndrome." (PMID 32443651, 2020). "For example, deletions of exons 1–9 or exons 1–17 of SHANK3 have been found in patients exhibiting severe language delay and significant intellectual disability." (PMID 29995933, 2018). "We have recently produced and validated the Shank3-deficient rat model, a novel transgenic rat model for ASD and intellectual disability that harbors a mutation in the Shank3 gene." (PMID 29970997, 2018). "The mutations in SHANK3 had the highest frequency (0.69%) in patients with ASD and profound intellectual disability." (PMID 28702161, 2017). "Intriguingly, mutations in SHANK3 are highly associated with intellectual disability and are especially abundant in patients suffering from ASD with moderate to profound intellectual disability." (PMID 27795858, 2016). "A recent study reported that a screen for SHANK3 mutations in 3,833 individuals with ASD and Intellectual disability (ID) revealed a prevalence of a mutation in the SHANK3 gene in over 2 % of this group." (PMID 26306707, 2015). "In contrast, the frequency and the penetrance of SHANK3 mutations in individuals with ASD and intellectual disability—more than 1 in 50—warrant its consideration for mutation screening in clinical practice." (PMID 25188300, 2014). "Given the high frequency and impact of SHANK3 mutations in individuals with ASD and intellectual disability—more than 1 in 50—this gene should be screened for mutations in clinical practice." (PMID 25188300, 2014). "Studies in intellectual disability and developmental delay confirm this rate of SHANK3 haploinsufficiency in these disorders as well." (PMID 23758743, 2013). "Haploinsufficiency of SHANK3 is associated with ASD and mental retardation in human patients and results in altered synaptic plasticity and reduced social behaviors in mice." (PMID 23468870, 2013). "Deletions of ProSAP2/SHANK3 at chromosome 22q13 are one of the major genetic abnormalities in neurodevelopmental disorders, and mutations of ProSAP2/SHANK3 have been identified in patients with ASD, intellectual disability (ID) and schizophrenia." (PMID 22346768, 2012). "SHANK3 plays a pivotal role in synaptic development and function, explaining its association with hallmark neurological and behavioral traits of PMS, such as intellectual disability, ASD, and hypotonia." (PMID 40429797, 2025). "For example, the SHANK3 gene is the most common gene associated with ASD and SHANK3 mutations are reported in 0.7% of patients with ASD (2.1% if ASD is accompanied by moderate to profound intellectual disability)." (PMID 35456477, 2022). "However, even though intellectual disability and ASD were present in the majority of individuals with SHANK3 mutations, speech impairment and motor deficits were less severe than in 22q13 deletions, and renal abnormalities were absent." (PMID 33407854, 2021). "The putative association between ASD and PMS is of particular interest as the SHANK3 gene is one of the many implicated in the aetiology of idiopathic ASD with SHANK3 deficiency associated with 0.5 to 2% of cases of ASD and intellectual disability." (PMID 29126394, 2017).
Intellectual disability (continued). "Importantly, mutations in Shank family proteins (also known as ProSAP) such as Shank1, Shank2 and Shank3 have been implicated in ASD and intellectual disability." (PMID 28979184, 2017). "Mutations in SHANK3 have also been found in schizophrenia and non-syndromic intellectual disability." (PMID 21779178, 2011). "According to a meta-analysis, monogenic mutations in SHANK3, which encodes the major postsynaptic density (PSD) scaffolding protein at excitatory glutamatergic synapses, are found in approximately 0.69% of ASD cases and up to 2.12% of all moderate to profound intellectual disability cases." (PMID 34566559, 2021). "In Shank3 mice, an ASD model with established E/I imbalance related to mutations in synaptic scaffolding, recent work has shown reduced prefrontal functional connectivity to other higher order regions that were found to be predictive of intellectual disability and socio-communicative impairments." (PMID 30833582, 2019). "Haploinsufficiency of the Shank3 gene accounts for 0.5–2.0% of ASD and intellectual disability cases." (PMID 33468258, 2021). "Duplications of the genomic region including SHANK3 have been reported in case studies of individuals with schizophrenia, anxiety, OCD, intellectual disability, psychosis, ADHD, bipolar disorder, and epilepsy." (PMID 34188957, 2021). "Although her son was born from uncontrolled pregnancy with high blood levels of phenylalanine and poorly adhered to low-phenylalanine diet himself, he also escaped the intellectual disability (IQ 80–85) indicating a possible joint modifying role of p.Pro1591Ala in SHANK1 and p.Pro1716Thr in SHANK3." (PMID 34900593, 2021). "The clinical manifestations of SHANK3 deficiency include ASD, global developmental delay, delayed or absent speech, intellectual disability, and motor abnormalities." (PMID 34776852, 2021).
schizophrenia (78 papers, 2010 to 2025). A major psychotic disorder characterized by abnormalities in the perception or expression of reality. "For instance, ORY-1001 has shown efficacy in normalizing ASD-related and schizophrenia-related symptoms in Shank3-deficient and Setd1a-deficient mice, respectively." (PMID 40102613, 2025). "Several studies suggest that Shank3 deletions and duplications are both linked to ASD and schizophrenia, suggesting that opposite changes in Shank3 levels produce similar or overlapping psychiatric phenotypes." (PMID 35266450, 2022). "Different SHANK3 mutations associated with ASD or schizophrenia in these two mutant mouse lines exhibited both distinct and shared defects at molecular, synaptic, circuit and behavioral levels." (PMID 32521803, 2020). "Peykov and colleagues identified a rare causative SHANK2 variant (SHANK2A1731S) in schizophrenia, and several groups have found missense mutations in SHANK3 in schizophrenia." (PMID 33343614, 2020). "Mutations in SHANK3 have also been found in four individuals from two families with atypical schizophrenia associated with early onset and ID." (PMID 29719671, 2018). "Specifically, synaptic adhesion molecules and their associated scaffold proteins, such as neurexin-1α, neuroligin-4 and Shank3, are among the few synaptic genes that are frequently identified as causative factors for ASDs and schizophrenia." (PMID 27812321, 2016). "Mutations in NRXN1, NRXN2, NLGN2, NLGN4, and SHANK3 genes related to ASD have been also found in schizophrenia patients." (PMID 25780553, 2015). "SHANK3 mutations have been identified in patients suffering from schizophrenia and bipolar disorder." (PMID 25188300, 2014). "Recently, de novo missense and nonsense mutations in SHANK3 have been described in atypical schizophrenia (with mild to moderate intellectual disability, early onset and dysmorphic features)." (PMID 21167025, 2010). "There is also evidence that genetic variants common to schizophrenia and autism spectrum disorder, such as mutations in the SHANK3, NRXN1, and CNTNAP2 genes, may contribute to the occurrence of autistic phenotypes in some patients with schizophrenia." (PMID 40724876, 2025). "Notably, de novo mutations of Shank3 have been reported in cases of schizophrenia and schizoaffective disorder; specifically, the R1117X mutation can cause loss of function of the Shank3 protein." (PMID 36831241, 2023). "Moreover, a recent study generated two novel SHANK3 mutant mouse lines harboring SHANK3 mutations that are found in patients with schizophrenia." (PMID 32521803, 2020). "In addition, there is a single report of two families ascertained for schizophrenia with mutations in SHANK3; affected individuals also had ID." (PMID 29719671, 2018). "Some of the mutations of the genes related to ASD, including NRXN1, NRXN2, NLGN2, NLGN4, SHANK3, and SynGAP, have been also found in the schizophrenia patients; for instance, two de novo mutations (R1117X and R536W) were identified in the SHANK3 gene of two families of schizophrenia." (PMID 25780553, 2015). "Indeed, cell lines derived from human patients are already available for mutations related to ASD such as SHANK3, as well as for Fragile X, Rett syndrome, Down syndrome, and schizophrenia." (PMID 24904277, 2014). "These evidences suggest that phenotypic variations as a result of SHANK3 mutations are quite broad and that ID, ASDs and schizophrenia may share common etiological factors." (PMID 22509352, 2012).
schizophrenia (continued). "Furthermore, altered HCN-cAMP signaling in prefrontal cortex networks also appears to contribute to the working memory deficits in schizophrenia and stress, while mutations in SHANK3 linked to schizophrenia may induce an HCN channelopathy." (PMID 39434909, 2024). "Intriguingly, transgenic expression of HERV-W ENV also led to impaired expression of several other genes that are implicated as genetic risk factors of schizophrenia and ASD, including Cacna1g, Ank3, Shank1, and Shank3." (PMID 40102613, 2025). "SHANK3 mutations cause many neuropsychiatric disorders, including the Phelan–McDermid syndrome (which arises from a deletion or point mutation in one copy of the SHANK3 gene), ASD, and schizophrenia." (PMID 38002499, 2023). "Proteomic and genomic evidence involving PSD-associated proteins and genes implicated in schizophrenia showed altered differentially expressed NMDA-interacting proteins, such as Shank3, known to contribute to the pathophysiology of the disease." (PMID 36831241, 2023). "Dysfunction of the SHANK3 gene is thought to be the primary cause of PMS, as patients with SHANK3 mutations manifest various neurodevelopmental and psychiatric conditions such as ID, ASD, and schizophrenia." (PMID 35743796, 2022). "SH3 and multiple ankyrin repeat domains 3 (SHANK3) deficiency in humans is associated with language and social communication problems of ASD, Phelan–McDermid syndrome, and schizophrenia." (PMID 35726297, 2022). "SHANK3 (ProSAP2) is one of the most common genes associated with ASD and is implicated in bipolar disorder, schizophrenia, and Alzheimer’s disease." (PMID 31451607, 2019). "Given the well-known association between SHANK3 and various neurodevelopmental disorders, including ASD, PMS and schizophrenia, we first subjected Emx1-Cre; Shank3Δ14–16 mice to behavioral tests in the social domain." (PMID 31649512, 2019). "Two human mutations in exon 21 have also been recreated in Shank3 KI models, the ASD-related InsG and the Schizophrenia (Schz)-related R1117X." (PMID 30911366, 2019). "First, to the best of our knowledge, mutations with large risk to schizophrenia have been reported in at least five genes, DISC1, NRXN1, PRODH, SHANK3, and SLC1A1 according to records in OMIM." (PMID 30745909, 2018). "A very nice example of this is a thorough evaluation of SHANK3 ASD and schizophrenia mutations in mouse models showing both shared and distinct defects in synaptic transmission, behavior, and spine density." (PMID 30123108, 2018). "Mutations in the genes of several components of this complex, especially Shank3 and Neuroligin 3 and 4, are linked to several genetic-associated neurodevelopmental disorders, in particular, ASD and schizophrenia." (PMID 30586380, 2018). "The susceptibility genes (such as DISC1, RELN, GABA, SHANK3, NRXN1, NTNG1, etc.), which were associated with schizophrenia, also confer risk to ASD." (PMID 26204268, 2015). "In addition to including members of the Set1-like H3K4 methyltransferase family (Kmt2a, Kmt2b, Kmt2c, and Kmt2d), these modules also encompassed rare variant genes associated with schizophrenia and ASD (Setd1a, Cacna1g, Ank3, Shank1, and Shank3)." (PMID 40102613, 2025). "Mutations in the gene encoding for Shank3 have been reported in ASD patients, and a variety of point mutations and small deletions of Shank3 have been causally associated with numerous neurodevelopmental and neuropsychiatric disorders, including schizophrenia." (PMID 36831241, 2023). "Moreover, duplications of Shank3 have also been reported in patients with bipolar disorder and schizophrenia." (PMID 36831241, 2023).
schizophrenia (continued). "For example, mice with overexpression of SH3 and multiple ankyrin repeat domains 3 (SHANK3), a gene associated with schizophrenia pathogenesis, exhibited mania-like behaviours and enriched ribosome-related genes as identified in The Kyoto Encyclopedia of Genes and Genomes (KEGG) gene library." (PMID 35806181, 2022). "Nevertheless, we found a number of genes in this list that have a reported association to schizophrenia or other neuropsychiatric disorders, for example, TENM4, NXN, NRXN1, GALNT5, SHANK3 and RELN." (PMID 36711134, 2022). "Furthermore, mutations in the Shank3 gene can cause not only ASD-like phenotype but also symptoms of other disorders such as schizophrenia and Rett syndrome About 75% of people with heterozygous mutation in Shank3 gene have been diagnosed with ASD." (PMID 35884680, 2022). "Thus, we identify two cellular phenotypes that exhibit the same pattern of dose sensitivity that is observed for Shank3 in schizophrenia and ASD." (PMID 28477407, 2017). "We next measured NLGN3 and SHANK3 mRNA expression levels in immortalized lymphoblastoid cells from 45 patients with schizophrenia and 45 healthy controls to examine the disease specificity of the differential expression levels between patients and healthy controls." (PMID 21615902, 2011). "It will be of interest to better understand the frequency of ASD and the characteristics of social deficits in SHANK3-haploinsufficiency syndromes, as it is already evident that this is not a universal finding in these syndromes when considering 22q13DS or schizophrenia." (PMID 21167025, 2010). "Abnormalities concerning tasks depending on sensorimotor function have been described in SHANK3-deficient rodents of the deletion models ex4-22|ALL, ex4-9|ANK, ex11|SH3, and ex13-16|PDZ, or mice harboring schizophrenia- and ASD-associated mutations (ex21|PRO-R1117X, -InsG3680 or -InsG3728)." (PMID 34784886, 2021). "Consistent with our findings, ORY-1001 has also been shown to restore H3K4me2 levels in the brains of Shank3-deficient and Setd1a-deficient mice, suggesting that normalization of reduced H3K4me2 levels may be a key mechanism by which ORY-1001 alleviates ASD- and schizophrenia-related dysfunctions." (PMID 40102613, 2025). "The interaction with SHANK3 might hint towards a participation of RICH2 in synaptic pathways associated with neuropsychiatric diseases since PSD scaffolding proteins of the SHANK family have been closely associated with Autism Spectrum Disorders (ASD) and Schizophrenia (SCZ)." (PMID 26969129, 2016). "In the same way, 22q13 duplications involving SHANK3 were reported in patients with Asperger syndrome, attention deficit-hyperactivity disorder (ADHD) or schizophrenia, suggesting that an overexpression of this gene could be also pathogenic." (PMID 28174603, 2017). "22q13 duplications spanning Shank3 are found in ASD, schizophrenia, ADHD, and bipolar disorder." (PMID 28477407, 2017). "Our study reveals reduced levels of NLGN3 and SHANK3 mRNA expression in lymphoblastoid cell lines derived from individuals with ASD, but not from those of individuals with schizophrenia." (PMID 21615902, 2011).